SPOCK2 (SPARC (osteonectin), cwcv and kazal like domains proteoglycan 2)
Diseases named in the same sentence as SPOCK2 in open-access papers (continued):
Sharing a sentence is not in itself a finding about the gene and the disease.
COVID-19 (2 papers, 2022 to 2024). A disease caused by infection with severe acute respiratory syndrome coronavirus 2. "In contrast to the genes downregulated in ILCs from COVID-19 patients, we observed an upregulation of SPOCK2 in ILC1 (adj.p = 6.7e-24), ILC2 (adj.p = 1.2e-37) and ILCp (adj." (PMID 39026668, 2024).
B-cell lymphoma (1 paper, 2025). "Top proteins specifically associated with non-germinal center-derived B-cell lymphoma included FCMR, SPOCK2, IGSF3 and SEMA4A." (PMID 40894013, 2025).
basal cell carcinoma (1 paper, 2024). A carcinoma involving the basal cells. "We further explored the expression of SPOCK2 in some tumors, including basal cell carcinoma (BCC), liver hepatocellular carcinoma (LIHC), prostate adenocarcinoma (PRAD), and squamous cell carcinoma (SCC)." (PMID 38535087, 2024).
cardiac hypertrophy (1 paper, 2023). "The genes that were most highly expressed in only a single-cell type were Gm20658 (fibroblasts), Ucp3 (cardiomyocytes), Spock2 (endocardial cells), Irf7 (endothelial cells), and Ifi206 (macrophages), of which Ucp3 and Irf7 were involved in heart failure and pathological cardiac hypertrophy." (PMID 37010266, 2023).
cervical cancer (1 paper, 2021). A primary or metastatic malignant neoplasm involving the cervix. "Interestingly, SPOCK2 has not been reported to be associated with cervical cancer, suggesting that SPOCK2 is a valuable research direction." (PMID 34030694, 2021).
colon adenocarcinoma (1 paper, 2022). "We then found increased expression of SPOCK1 but not SPOCK2 was associated with poor overall survival (OS) in human colon adenocarcinoma (COAD)." (PMID 35046388, 2022).
epilepsy (1 paper, 2023). A brain disorder characterized by episodes of abnormally increased neuronal discharge resulting in transient episodes of sensory or motor neurological dysfunction, or psychic dysfunction. "No studies in the same field have confirmed the role of SPOCK2, CTSZ and HLA-DMB in epilepsy or stress cardiomyopathy." (PMID 36776884, 2023).
heart failure (1 paper, 2023). Inability of the heart to pump blood at an adequate rate to meet tissue metabolic requirements. "However, the association of Gm20658, Spock2 and Ifi206 with myocardial fibrosis or heart failure has not been previously reported." (PMID 37010266, 2023).
lung carcinoma (1 paper, 2020). "To further study the potential role of SPOCK2 in lung cancer, we downloaded datasets from the TCGA database." (PMID 33244319, 2020). "In addition, the expression of SPOCK2 can be induced by interferon (IFN), which plays a vital role in immune responses in lung cancer." (PMID 33244319, 2020).
myopia (1 paper, 2024). "According to our research, patients with pathologic myopia had downregulated expression of XYLT1, VCAN, and SPOCK2 and upregulated expression of TUBA1A and EEF1A1." (PMID 39160465, 2024).
ovarian endometriosis (1 paper, 2023). A non-neoplastic disorder characterized by the growth of endometrial tissue in the ovaries. "Another study reported that epigenetic inactivation of SPOCK2 caused by SPOCK2 hypermethylation, may be associated with the exacerbation of ovarian endometriosis." (PMID 36629984, 2023).
Pan (1 paper, 2024). "Pan-cancer expression of SPOCK2 was determined using the TISCH database." (PMID 38535087, 2024).
progressive supranuclear palsy (1 paper, 2024). A rare late-onset neurodegenerative disease characterized by supranuclear gaze palsy, postural instability, progressive rigidity, and mild dementia. "Additionally, we identified a mutant form of Brd4 in Progressive supranuclear palsy patients, which attenuates the ability of Brd4 to promote cell competition by disrupting its interaction with the promoter of Spock2." (PMID 39010274, 2024).
retinopathy of prematurity (1 paper, 2017). A bilateral retinopathy characterized by neovascularization, scarring, retinal detachment, and eventually blindness. "Levels of THBS1, MMP8, MMP9, MMP25, TIMP2 and TIMP3 increased as severity of BPD and retinopathy of prematurity (ROP) increased, whereas ETS1, LEF1 and SPOCK2 exhibited the opposite trend." (PMID 28103583, 2017).
serous ovarian cancer (1 paper, 2024). "Kaplan–Meier analysis demonstrated that patients with PACA with high SPOCK2 mRNA expression had better OS than those with low expression, whereas patients with high-grade serous ovarian cancer with high SPOCK2 mRNA expression had worse OS than the OS of those with low expression." (PMID 38535087, 2024).
tumor (21 papers, 2014 to 2025). "SPOCK2 encodes an ECM protein often misregulated in tumor cells." (PMID 41397376, 2025). "Further investigation into the molecular mechanisms of SPOCK2’s role in LUAD revealed that this could be partially due to its association with tumor-infiltrating immune cells." (PMID 37841281, 2023). "In addition, we observed via the TIMER database that SPOCK2 expression was strongly associated with the immunomarkers of TIICs and that these correlations remained unchanged after tumor purity correction." (PMID 33244319, 2020). "In this study, expression levels of SPOCK2 in LUAD patient tumor tissues were remarkable lower than normal lung tissues, and high level of SPOCK2 expression predicted better survival." (PMID 36629984, 2023). "To elucidate the effect of SPOCK2 or SPRED1 on tumor growth of LUAD cells in vivo, we subcutaneously injected the SPOCK2 or SPRED1 overexpressed A549 cells into the nude mice." (PMID 36629984, 2023). "An increasing number of investigations focus on SPOCK2 in diverse malignancies, as it was reported to be an attractive tumor marker in cancer in 2008." (PMID 37188984, 2023). "The results revealed that the SPOCK2 mRNA expression level was lower in LUAD than in non-tumor lung tissue (P < 0.05)." (PMID 33244319, 2020). "We also explored SPOCK2 protein expression via the Clinical Proteomic Tumor Analysis Consortium (CPTAC) and Human Pathology Atlas Project (HPA) databases." (PMID 33244319, 2020). "We identified differential SPOCK2 expression in LUAD with T classification and SPOCK2 was negatively correlated with several clinical features including the pathological stage, tumor status, and lymph node status in LUAD patients." (PMID 33244319, 2020). "We found SPOCK2 was significantly downregulated in LUAD compared with that in non-tumor controls and was correlated with clinical parameters." (PMID 33244319, 2020). "We observed SPOCK2 was related to tumor stage (TNM classification) in LUAD using The Cancer Genome Atlas (TCGA) data." (PMID 33244319, 2020). "We also used data from Human Protein Profiles to demonstrate that the proteins encoded by seven immune-related genes were expressed at different degrees in HCC tissues, among which TMC8, BIN2, GIMAP7, and SPOCK2 were strongly to moderately positive in tumours." (PMID 32213661, 2020). "In view of miRNA functional mechanism and oncogenic roles of GJB2, S100A2 and SPOCK2, upstream miRNAs of the three genes should be tumor suppressive miRNAs." (PMID 31794425, 2019). "Moreover, SPOCK2 was positively associated with the infiltration levels of CD8+ T-cells, and played an important role in regulating tumor-infiltrating immune cells in LUAD." (PMID 38535087, 2024). "Overexpression of SPOCK2 or SPRED1 significantly restrained tumor growth." (PMID 36629984, 2023). "Interestingly, silencing of SPOCK2 leads to stimulation of proliferation and migration of cancer cells, indicating SPOCK2 serves as a tumor suppressor in PDAC." (PMID 37188984, 2023). "SPOCK2 staining displayed considerable heterogeneity in the BM+ tumor areas." (PMID 34203581, 2021). "Further, we tried to examine whether the tumor immune microenvironment was different in LUAD patients with high SPOCK2 levels compared to those with low levels." (PMID 33244319, 2020). "Therefore, in cancer disease, SPOCK3 reveals an anti-tumor invasion activity, whereas SPOCK2 reveals a pro-tumor invasion activity." (PMID 33287223, 2020). "Furthermore, TMC8, BIN2 and SPOCK2 protein levels were also consistently higher expressed in tumor tissues than those in normal liver tissues." (PMID 32213661, 2020). "Moreover, the association between SPOCK2 expression and the marker genes of TIICs validated the role of SPOCK2 in LUAD tumor immunity." (PMID 33244319, 2020). "Therefore, it is tempting to speculate that the expression of SPOCK2 results in changes of the microenvironment that facilitate tumor cell migration." (PMID 34203581, 2021).
tumor (continued). "Therefore, we examined the correlation of SPOCK2 expression with the tumor immune system in LUAD." (PMID 33244319, 2020). "The messenger RNA (mRNA) levels of these genes in the TCGA-GTEx cohort displayed that SPOCK2, LIPH, RARRES3, and EMP1 were significantly higher in tumor samples than in control tissues." (PMID 38535087, 2024). "Further analyses showed that the overexpression of SPOCK2 or that of SPRED1 statistically inhibited LUAD cells proliferation, migration ratio, invasion activity, and tumor growth." (PMID 36629984, 2023). "We intend to continue collecting human samples to validate the expression of SPOCK2 and SPRED1 in tumor tissues." (PMID 36629984, 2023). "Next, we evaluated the expression of SPOCK2 and SPRED1 in the LUAD samples from the TCGA database, and found that the expression of SPOCK2 and SPRED1 in the tumor tissues of LUAD patients was significantly decreased." (PMID 36629984, 2023). "Aberrant YTHDF2 upregulation markedly hampers expression of multiple m6A-marked tumor-suppressing transcripts, including CDKN2B and SPOCK2, and induces oncogenic reprogramming." (PMID 36973285, 2023). "Likewise, in our study, significant correlations were found between SPOCK2 expression and several markers of TIICs in LUAD, which indicated that SPOCK2 plays a significant role in regulating the tumor immune microenvironment." (PMID 33244319, 2020). "Moreover, overexpression of SPOCK2 or SPRED1 could inhibit tumoral proliferation, migration ratio, and invasion activity in vitro as well as retard tumor growth in vivo." (PMID 36629984, 2023).
cancer (14 papers, 2008 to 2025). A tumor composed of atypical neoplastic, often pleomorphic cells that invade other tissues. "Glycoprotein SPOCK2, involved in extracellular matrix formation, is critical for cell invasion and metastasis in cancer." (PMID 40375334, 2025). "As SPOCK2 was reported to undergo hypermethylation in some cancer entities in 2008, it has gained attention in this field." (PMID 37188984, 2023). "In recent years, a growing number of studies showed that SPOCK2 played significant roles in many cancers." (PMID 36629984, 2023). "The combination of NSE1 or SPOCK2 hypermethylation showed a sensitivity of 80% and specificity of 95% in differentiating cancer from normal." (PMID 18446232, 2008). "SPOCK2 is synthesized by lung epithelial cells and fibroblasts and localized in the extracellular matrix, which plays significant roles in limiting the malignant behavior of cancer cells." (PMID 36629984, 2023). "In 2008, a study first showed a link between the SPOCK2 gene and cancer." (PMID 36629984, 2023). "SPOCK2 correlates with the development and progression of various human cancers." (PMID 33244319, 2020). "Moreover, pan-cancer scRNA sequencing datasets from TISCH analysis indicated that SPOCK2 may be a novel marker of exhausted CD8+ T-cells." (PMID 38535087, 2024). "Interestingly, many of the DMGs identified had multiple roles and several were potential cancer biomarkers or were previously shown to be implicated in various types of cancers, including ABLIM1, ADAM12, ARHGEF4, FBLN2, ITGA6, LRPAP1, Ly9, NT5E, PITPNC1, PLCG1, OBSCN, RHOH, SPTBN1, SPOCK2 and SPRY1." (PMID 41159936, 2025). "More LUAD patient samples are needed to confirm the prognostic value of SPOCK2, and the function of SPOCK2 in TIIC regulation in cancers as well as its influence on the response to immunotherapy should be verified in future clinical trials." (PMID 33244319, 2020). "Among these genes, only expression levels of GJB2, S100A2, SPOCK2 and TGM1 were significantly upregulated in cancer samples and their high expression indicated poor prognosis (OS or RFS)." (PMID 31794425, 2019). "Thus, current work provides new insights into understanding the potential roles of EZH2-mediated SPOCK2 or SPRED1 in LUAD and their potential as biomarkers for cancer therapy and prognosis." (PMID 36629984, 2023).
infection (4 papers, 2022 to 2025). The state of being infected such as from the introduction of a foreign agent such as serum, vaccine, antigenic substance or organism. "SPOCK2/Testican2 production is Induced by interferon-α produced upon influenza virus infection, and has been shown to form a protective barrier against infection of neighboring cells." (PMID 39026668, 2024). "Differential gene expression analysis showed that increased amounts of Tfh2 are specifically enriched for Cxxc5 and Spock2 after infection." (PMID 37039643, 2023). "In contrast, the expression of SPOCK2 and ISG20 was upregulated following infection with both bovine- and mink-derived H5N1." (PMID 41157297, 2025).
SPOCK2 also shares sentences with these, for which no sentence is quoted: lung adenocarcinoma (6 papers); breast tumor (2); amyloid (1); biliary tract cancer (1); dementia (1); glomerulosclerosis (1); influenza infection (1); Intellectual disability (1); Myocardial fibrosis (1); neurodegenerative disease (1); non-small cell lung carcinoma (1); ovarian serous cystadenocarcinoma (1); pancreatic cancer (1); pancreatic ductal adenocarcinoma (1); prostate adenocarcinoma (1); schizophrenia (1); squamous cell carcinoma (1); stress cardiomyopathy (1); substance abuse (1).